ADA (adenosine deaminase)
Diseases named in the same sentence as ADA in open-access papers (continued):
Sharing a sentence is not in itself a finding about the gene and the disease.
Pleural effusion (133 papers, 2008 to 2026). The presence of an excessive amount of fluid in the pleural cavity. "Our previous studies revealed that age affected the diagnostic accuracy of NT-proBNP, adenosine deaminase (ADA), and cancer ratio in patients with pleural effusion." (PMID 40395336, 2025). "On the other hand, pleural effusion with ADA above 70 IU/L was associated with an increased likelihood of TBP compared to ADA between 40 and 70 IU/L, which is consistent with previous studies." (PMID 38178065, 2024). "Elevated ADA levels have been observed in samples of pleural effusion from varying causes: about two-thirds of cases of empyema and approximately one-third of cases of PPE are characterized by ADA levels surpassing 40 U/L." (PMID 38742106, 2024). "When there is suspicion of tubercular effusion, a commonly used diagnostic threshold to confirm a TB pleural effusion is a pleural fluid adenosine deaminase (ADA) level greater than 40 U/L." (PMID 39416574, 2024). "In cases with ADA ≥ 40 IU/L and < 70 IU/L, the most common cause of pleural effusion was PPE (35%), followed by sMPE (24%) and TBP (19%)." (PMID 38178065, 2024). "Combined detection of pleural effusion IL-33, ADA and peripheral blood T-SPOT.TB can improve the diagnostic efficacy of tuberculous pleurisy." (PMID 34425761, 2021). "Diagnostic performance of pleural effusion mononuclear cells count, ADA and combination diagnostic test (n = 205)." (PMID 31921874, 2019). "Most of the TB pleural effusion patients had raised ADA levels, making it a better diagnostic tool in suspected cases of pleural TB." (PMID 31016096, 2019). "This retrospective case-control study aimed to evaluate the diagnostic value of pleural effusion mononuclear cells count and its combination with ADA in TBP patients." (PMID 31921874, 2019). "Meanwhile, pleural effusion mononuclear cells count and ADA test were performed to evaluate the diagnostic value for TBP." (PMID 31921874, 2019). "We aimed to evaluate the diagnostic value of pleural effusion mononuclear cells count and its combination with adenosine deaminase (ADA) in TBP patients." (PMID 31921874, 2019). "The cause for this latter discrepancy was the difficulty in recruiting new patients with such a relatively infrequent cause of pleural effusion which, in addition, had to exhibit elevated ADA concentrations." (PMID 26962828, 2016). "Some researchers present that the pleural thickening degree is associated with elevated protein and adenosine deaminase (ADA) in pleural effusion." (PMID 24885536, 2014). "On the contrary, Rafael concluded that the ADA assay should be considered as a screening test to guide further diagnostic procedures in cases of exudative pleural effusion." (PMID 21811524, 2010). "In an era where immunocompromised hosts are increasing, cryptococcal infection should be considered as a potential aetiology in immunosuppressed patients with an exudative pleural effusion of unknown cause, even if ADA levels are elevated." (PMID 38371460, 2024). "Alternatively, ADA levels may be higher in pleural effusions caused by autoimmune diseases such as rheumatoid arthritis and systemic lupus erythematosus." (PMID 38750432, 2024). "Adenosine deaminase (ADA) in pleural effusion is a widely accepted diagnostic marker for TBP." (PMID 38178065, 2024). "Both the sensitivity and specificity of pleural effusion sCD46, sCD55, sCD59, and ADA perform with equivalent diagnostic effects, and combine detection improved the diagnostic accuracy, suggesting that they can be used as biomarkers for differentiating TPE and non-TPE." (PMID 36820087, 2023). "In this study, the pleural effusion in the patients with EF-PE was found to be positive for Rivalta test, and was associated with elevated levels of total protein and adenosine deaminase, indicating that the pleural effusion was an exudate in the patients with EP-PE." (PMID 37012347, 2023). "ADA is diagnostic even in HIV positive patients with TB pleural effusion." (PMID 31016096, 2019).
Pleural effusion (continued). "Clinicians need to be aware of the usefulness and limitations of the anti-mycoplasma antibody test and closely examine the possibility of tuberculous pleurisy before judging that lymphocyte-dominant pleural effusion with a high ADA level is caused by M pneumoniae infection." (PMID 29768381, 2018). "Moreover, receiver operator characteristic analysis was performed to evaluate the diagnostic accuracy of pleural effusion adenosine deaminase." (PMID 27276396, 2016). "Pleural fluid adenosine deaminase (ADA) has thus become an important diagnostic tool in the evaluation of exudative pleural effusions because it is inexpensive, rapid and has a high accuracy with sensitivity and specificity of up to 100% and % respectively for diagnosis of TPE." (PMID 24238276, 2013). "Recent studies have shown that the ADA level may be higher in pleural effusion caused by empyema, malignant tumors, or autoimmune diseases such as rheumatoid arthritis and systemic lupus erythematosus because of the abundance of lymphocytes in these types of effusion." (PMID 38750432, 2024). "Thus, the diagnostic accuracy of IL-27.ADA levels in pleural effusion was 98.86% (87/88)." (PMID 33436672, 2021). "Imaging demonstrated a left pleural effusion, and thoracentesis revealed a lymphocytic exudate with elevated adenosine deaminase." (PMID 42100439, 2026). "We describe a 44‐year‐old woman whose initial manifestation of seropositive RA was a large, unilateral, neutrophil‐rich, adenosine‐deaminase (ADA)-positive pleural effusion." (PMID 41669585, 2026). "The study was an observational study aimed at assessing diagnostic value of adenosine deaminase (ADA) and Cartridge-Based Nucleic Acid Amplification Test (CBNAAT) in 200 patients with pleural effusion in a tertiary care center." (PMID 42109401, 2026). "The characteristic of pleural effusion in non-Hodgkin lymphoma is exudative with increased lymphocytes and an elevated level of ADA, which is similar to tuberculous pleurisy." (PMID 41480553, 2025). "A 54-year-old male presented with a large, left-sided hemorrhagic exudative pleural effusion characterized by lymphocytic predominance and a low adenosine deaminase (ADA) level." (PMID 40196057, 2025). "Still, lymphoma’s pleural invasion also leads to more lymphocytes in the pleural effusion, which increases the ADA concentration." (PMID 40423034, 2025). "Other analyses of the pleural effusion indicated the following: ADA: 48 U/L, LDH: 561 U/L, glucose: 5.29 mmol/L, protein: 30.6 g/L, and Cellular Keratin 19 Fragment (CYFRA21-1): 12.85 ng/mL." (PMID 41480553, 2025). "In contrast, adenosine deaminase (ADA) activity was significantly elevated in infection-related pleural effusion." (PMID 40170018, 2025). "The ADA level in the pleural effusion of this patient was 48 U/L in the local hospital and 102 U/L in our hospital, which is consistent with the results of previous studies." (PMID 41480553, 2025). "The pleural effusion was an exudate composed primarily of mononuclear cells with elevated adenosine deaminase (ADA) and lactate dehydrogenase (LDH)." (PMID 41480553, 2025). "Thoracentesis revealed an exudative pleural effusion with a predominant lymphocyte count of 89% and adenosine deaminase (ADA) levels of 49 U/L." (PMID 40161186, 2025). "The presumptive diagnosis of TPE has traditionally relied on the predominance of lymphocytes and a high concentration of adenosine deaminase (ADA) in pleural effusion." (PMID 38742106, 2024). "The ultrasound-guided aspiration of pleural effusion with the evaluation of the lymphocyte count and the adenosine deaminase (ADA) level within the pleural fluid can support the diagnosis of tuberculous pleurisy." (PMID 38611619, 2024). "As a result, researchers have investigated various biomarkers in pleural effusion, such as adenosine deaminase (ADA) and interferon-gamma (IFN-γ)." (PMID 39445216, 2024).
Pleural effusion (continued). "For predicting hematologic MPE in pleural effusion with ADA ≥ 150, a combination of PMN < 50% and serum LD ≥ 2 × serum ULN presented corresponding values of 0870, 0.857, 0.952, 0.667, and 0.860." (PMID 38178065, 2024). "In summary, the ADA/CRP ratio has great potential as an additional biomarker for assessing pleural effusions." (PMID 39205740, 2024). "We describe a 59-year-old male heart transplantation recipient who presented with a mononuclear-leukocyte-predominant exudative pleural effusion, with adenosine deaminase levels (ADA) of 37 IU/L and focal pleural nodularity on computed tomography." (PMID 38371460, 2024). "In pleural effusion with ADA levels ranging between 40 IU/L and 150 IU/L, a pleural lymphocyte proportion ≥ 35% and a pleural LD/ADA ratio < 18 are strong indicators of TBP." (PMID 38178065, 2024). "Pleural fluid investigations suggested exudative pleural effusion with low adenosine deaminase (ADA) according to light criteria." (PMID 39310451, 2024). "Nonetheless, pleural lymphocytic infiltration secondary to lymphoma also leads to an increase in pleural effusion ADA levels, with 25–56% of lymphomatous pleural effusions demonstrating ADA levels above the standard TB cutoff." (PMID 38178065, 2024). "Typically, IgG4‐related pleural effusions are lymphocyte‐predominant exudative effusions with mild elevation of adenosine deaminase (ADA)." (PMID 38887429, 2024). "The developed prediction model included age, positive T-SPOT.TB result, logarithm of the ratio of mononuclear cells to multiple nuclear cells in pleural effusion (lnRMMPE), and adenosine deaminase in pleural effusion ≥ 40 U/L." (PMID 37407665, 2023). "The level of ADA in the pleural effusion can belowered in the elderly, the critical ill, as well as inpatients with multiorgan dysfunction." (PMID 38084235, 2023). "Most cases revealed a high leukocyte count with a low percentage of lymphocytes and elevated ADA levels in the pleural effusion." (PMID 37337175, 2023). "The pleural effusion in the eight patients with EF-PE was found to be positive for Rivalta test, accompanied by elevated levels of total protein and adenosine deaminase (normal reference range: 0–24 μ/L)." (PMID 37012347, 2023). "In other reports, pleural effusion tests were similar to tuberculous pleurisy with a high percentage of lymphocytes and elevated ADA levels which still would remind you of the possibility of nontuberculous Mycobacterium infection." (PMID 37337175, 2023). "Based on the high value of adenosine deaminase (ADA), we tentatively diagnosed tuberculous pleurisy for the large pleural effusion and treated her well with the initiation of four antituberculosis drugs." (PMID 36632275, 2022). "A recent study showed that the specificity and sensitivity combined pleural effusion IL-33 detection, ADA detection and the peripheral blood T-SPOT test were 100% and 88.5%, respectively." (PMID 36111237, 2022). "To date, lymphocyte-dominated exudative pleural effusion with a high level of ADA has been considered an indication of tuberculous pleuritis." (PMID 33926544, 2021). "The main strength of this study is the possibility of diagnosis and discrimination of pleural effusions using cost-effective and widely available biomarkers (p-ADA, p-CRP)." (PMID 34575641, 2021). "We report a case of IgG4-related pleural effusion with a high concentration of ADA in the pleural effusion." (PMID 33726002, 2021). "Correlation between pleural fluid IL-33, pleural effusion ADA and peripheral blood T-SPOT.TB was analyzed, comparison of the three separate and combined diagnostic efficacy was also performed." (PMID 34425761, 2021). "The AUC of pleural effusion ADA and MNC/LEU ratio were 0.810 (0.749–0.870) and 0.776 (0.712–0.839), respectively, and there was no statistical difference between the two groups (P = 0.446)." (PMID 33816527, 2021).
Pleural effusion (continued). "Recently, some research showed some IgG4-related pleuritis cases with elevated adenosine deaminase in pleural effusion." (PMID 34425761, 2021). "Chest computed tomography (CT) revealed left pleural effusion that was exudative and predominant with lymphocytes, elevated adenosine deaminase (ADA) and Class III cytology (malignancy suspected)." (PMID 33926544, 2021). "AUC for combined detection of pleural effusion IL-33, ADA and peripheral blood T-SPOT.TB is the largest, with a value of 0.962." (PMID 34425761, 2021). "Among these exudative pleural effusion 92.2% (83/111) study subjects had positive ADA level, and 81% (90/111) were responded to anti tubercular therapy." (PMID 34125834, 2021). "Levels of pleural fluid adenosine deaminase (ADA), a useful marker for the diagnosis of tuberculous pleurisy, are elevated in some reports of immunoglobulin G4 (IgG4)-related pleural effusion." (PMID 33726002, 2021). "In summary, this study compared the AUC, sensitivity and specificity of pleural effusion IL-33, ADA and blood TSPOT for the diagnosis of tuberculous pleurisy." (PMID 34425761, 2021). "Most TB infections were confirmed by the sputum culture (58.8%) followed by extra-pulmonary sites culture (12.3%), extra-pulmonary sites biopsy (7.9%), lung biopsy (7.0%), and pleural effusion ADA concentration more than 40 U/L (4.4%)." (PMID 34485344, 2021). "Diagnostic value of combined detection of GSDMD, ADA, and LDH for pleural effusion differential diagnosis." (PMID 34163438, 2021). "In a recently published case-based review, IgG4-related pleural effusion has been reported in 17 patients and in pleural effusion sampling, adenosine deaminase levels were found to be high." (PMID 32777900, 2020). "The pleural effusion contained elevated concentrations of adenosine deaminase (ADA) and lactate dehydrogenase (LDH), and results of a Rivalta test for pleural effusion and M. tuberculosis DNA tests were positive." (PMID 32667282, 2020). "Typical manifestations of TPE are well-recognised, including submassive, unilateral pleural effusion with lymphocyte predominance and high ADA." (PMID 31937286, 2020). "Two hundred seventy-four consecutive adult patients with pleural effusion were selected from Beijing and Wuhan between January 1, 2014 and June 30, 2015, and their pleural fluid concentrations of ADA, IFN-γ, and IL-27 were tested." (PMID 32571326, 2020). "This study further explored combination of pleural effusion mononuclear cells count and ADA test in order to improve the accuracy of TBP diagnosis." (PMID 31921874, 2019). "Some other commonly used indexes, such as percentage of lymphocyte and adenosine deaminase (ADA) level in pleural effusion, have limited value in diagnosing plTB because of low sensitivity or specificity." (PMID 30761274, 2019). "Simultaneous cross-sectional studies can be used in the future to further investigate the value of combination test of pleural effusion mononuclear cells count and ADA for the diagnosis of TBP." (PMID 31921874, 2019). "The ADA levels easily differentiate TB pleural effusion from parapneumonic, malignant, pancreatic, and amoebic pleural effusions." (PMID 31016096, 2019). "The difference suggested that combination of pleural effusion mononuclear cells count and ADA test were better than pleural effusion mononuclear cells count was used alone for TBP diagnosis." (PMID 31921874, 2019). "Another report revealed that the sensitivity and specificity of the proportion of lymphocytes (LP ≥ 50%) in pleural effusion combined with ADA greater or equal to 40 U/L for TBP were 86.3 and 98.3%, respectively." (PMID 31921874, 2019). "Other pleural effusion parameters, such as ADA and LDH, had also been evaluated in previous studies." (PMID 31272486, 2019). "In our patient, lymphocytes were the dominant cell fraction and the ADA level was high in the pleural effusion, and anti-mycoplasma antibody results were positive, which served as a red herring." (PMID 29768381, 2018).
Pleural effusion (continued). "Tuberculous pleurisy is one of the most important differential diagnosis in cases with pleural effusion under investigation with high ADA levels." (PMID 30148839, 2018). "Forty-eight HIV positive patients with pleural effusion were evaluated; ADA assay was obtained in forty-three of them." (PMID 30428535, 2018). "Exudative pleural effusion with lymphocyte dominance and a high adenosine deaminase level in M pneumoniae infection have been reported." (PMID 29768381, 2018). "Lymphocyte dominance and a high ADA level in M pneumoniae infection-induced pleural effusion, which have been reported, also contributed to the misdiagnosis." (PMID 29768381, 2018). "Among the 18 patients diagnosed as TB pleuritis according to the diagnostic criteria, 11 patients were diagnosed as TB pleuritis besed on the ADA and lymphocyte neutrophil ratio in pleural effusion." (PMID 28968445, 2017). "Combined use of ADA and the lymphocyte-neutrophil ratio (LNR) was found to be more useful than use of ADA alone, especially in TB pleural effusion 8,9,15." (PMID 27759851, 2016). "The ADA levels in TB pleural effusion are significantly higher compared to those in para-pneumonic, malignant pleural and transudative effusions." (PMID 27759851, 2016). "In TB pleural effusion, when ADA (≥50 IU/L) is combined with the LNR (≥0.75), the sensitivity and specificity increase 8,15." (PMID 27759851, 2016). "The pleural effusion was sampled by thoracocentesis and then sent for adenosine deaminase testing, biochemical testing and microbiological culture." (PMID 27276396, 2016). "In the present study, significantly elevated ADA activity was observed in the exudative pleural effusion of the patient." (PMID 25667674, 2015). "The present study reports the case of a 78-year-old patient who initially presented with bilateral pleural effusion and elevated adenosine deaminase (ADA) activity, but was ultimately diagnosed with MPE." (PMID 25667674, 2015). "A number of studies have analysedADA and its isoenzymes in pleural effusions, and have found that ADA-2 isoenzyme is primarily responsible for the total ADA activity in tuberculous effusions, while ADA-1 is the major isoenzyme in parapneumonic effusions." (PMID 24602306, 2014). "He returned to our hospital where his pleural effusion was found to be positive for adenosine deaminase (ADA), and he was diagnosed with a tuberculosis infection." (PMID 25705401, 2013). "ADA levels by type of pleural effusion in three tuberculosis pleural effusion prevalence periods (1998–2000, prevalence: 31.3%; 2001–2004, prevalence: 11.8%; and 2005–2008, prevalence: 7.4%)." (PMID 22723878, 2012). "We have found the pleural fluid ADA levels to be consistently increased and more than the cut-off (40U/L) in cases of exudative pleural effusions of tuberculous etiology." (PMID 21811524, 2010). "Jadhav and Bardapurkar concluded that ADA is a useful biochemical marker to evaluate exudative pleural effusions." (PMID 21811524, 2010). "Considering this a prospective hospital based study was designed to compare pleural fluid adenosine deaminase level and pleural biopsy in establishing the diagnosis of tubercular pleural effusion." (PMID 20165661, 2008). "However, pleural TB is a frequent misdiagnosis when lymphoma presents with pleural effusion due to the high level of ADA in the pleural fluid." (PMID 40423034, 2025). "In this regard, some studies have shown that an increase in the concentration of ADA in the pleural effusion may indicate lymphoma." (PMID 40423034, 2025). "Therefore, the degree of increase in LDH and ADA in pleural effusion can help estimate the nature of the effusion before a pathological diagnosis is confirmed." (PMID 41480553, 2025). "However, this patient had greatly an exudative pleural effusion with raised adenosine deaminase levels highly suggestive of extrapulmonary tuberculosis." (PMID 39697914, 2024).